TRAJ39 (T cell receptor alpha joining 39)
Gene: T-cell receptor joining (J) gene on chromosome 14 (22,501,601 to 22,501,663, forward strand). Ensembl gene ENSG00000211850.
Diseases named in the same sentence as TRAJ39 in open-access papers:
TRAJ39 is named in the same sentence as 1 disease in open-access papers, as found by Europe PMC text mining. Sharing a sentence is not in itself a finding about the gene and the disease. The quoted sentences say what the papers report.
COVID-19 (1 paper, 2025). A disease caused by infection with severe acute respiratory syndrome coronavirus 2. "Nine out of the ten combinations that contributed most to the variability fell on the negative axis of PC1, and included TRAV9-2 × TRAJ30 and TRAV26-1 × TRAJ39, which both showed increased proportional usage in the COVID-19 CD4 repertoires compared to healthy controls." (PMID 40331338, 2025).